STC2 (stanniocalcin 2)
Diseases named in the same sentence as STC2 in open-access papers (continued):
Sharing a sentence is not in itself a finding about the gene and the disease.
hepatocellular carcinoma (25 papers, 2019 to 2025). A malignant tumor that arises from hepatocytes. "The relative expression level of STC2 in hepatocellular carcinoma tissue is associated with tumor size, hepatocellular carcinoma stage, metastasis, and differentiation." (PMID 34599150, 2021). "STC2 expression was found to be associated with hepatocellular carcinoma tumor microsatellite instability in our study, which may provide a further therapeutic strategy for immunotherapy of hepatocellular carcinoma patients." (PMID 36685853, 2022). "Further studies unraveled that STC2, like Nrf2, functions as a dominant tumor-promoter, because STC2-leading increases in clonogenicity of hepatoma cells and malgrowth of relevant xenograft tumors were almost completely abolished in STC2-/- cells." (PMID 40703332, 2025). "For example, the Nur77/ΔDBD gene was reported to downregulate stanniocalcin 2 (STC2) overexpression in hepatocellular carcinoma, which increased the expression of P-gp and Bcl-2." (PMID 37497002, 2023). "The expression of STC2 also regulates the switch from G1 to S and the protein levels of cyclin D1 and pERK1/2, thus, indicating that STC2 has a direct role in the progression and metastasis of hepatocellular carcinoma." (PMID 34599150, 2021). "The results of immunohistochemistry showed that the protein expression levels of HDAC1, BIRC5, SPP1, STC2 in hepatocellular carcinoma tissues were higher than those in normal tissues." (PMID 34616672, 2021). "Studies have shown that high expression of STC2 promotes hepatocellular carcinoma proliferation and induces drug resistance, resulting in poor prognosis." (PMID 32411183, 2020). "STC2 expression also regulated G1 to S phase transition and altered protein levels of cyclin D1 and pERK1/2 suggesting direct role of STC2 in hepatocellular carcinoma progression and metastasis." (PMID 32296395, 2020). "The hepatocellular carcinoma patients with higher expression of STC2 also had shorter median survival time." (PMID 32296395, 2020). "STC2 promoted proliferation in many kinds of cells, for example, STC2 promoted hepatocellular carcinoma proliferation in vitro and hepatocellular carcinoma cells proliferation." (PMID 32759741, 2020). "Both STC2 mRNA and protein expression were related to tumor size, stage, metastasis, and differentiation in hepatocellular carcinoma." (PMID 32296395, 2020). "STC2 was up-regulated in hepatocellular carcinoma, promoting cell proliferation and migration in vitro." (PMID 32579175, 2020). "Further study also revealed that the overexpression of STC2 predicted poor prognosis in nasopharyngeal carcinoma, laryngeal squamous carcinoma, and hepatocellular carcinoma." (PMID 32258098, 2019). "Since previous study revealed STC2 may function in neck squamous cell carcinoma, gastric cancer, and hepatocellular carcinoma, we tend to perform pan-cancer analysis to uncover the oncogenic roles of STC2." (PMID 40535801, 2025). "Additionally, expression of STC2 was correlated with tumor invasion, metastasis and size in gastric cancers and hepatocellular carcinoma." (PMID 32296395, 2020). "STC2 overexpression in hepatocellular carcinoma could lead to poor prognosis, which might be due to its induced increase of P-glycoprotein and Bcl-2 protein expression levels." (PMID 32579175, 2020). "Furthermore, ectopic expression of STC2 promoted hepatocellular carcinoma cell proliferation and colony formation." (PMID 32296395, 2020). "Five genes (PSRC1, SOCS2, TMEM45A, CCT5, and STC2) were selected from the TCGA training dataset to construct the prognostic CSGscore signature, which could precisely predict the prognosis of hepatocellular carcinoma patients both in the training and validation datasets." (PMID 36589233, 2022). "Recent studies have indicated that STC2 plays an important role in the occurrence and development of hepatocellular carcinoma and contributes to the development of new HCC treatment strategies." (PMID 34616672, 2021).
hepatocellular carcinoma (continued). "We then validated the expression of each lncRNA in a group of mixed origin cancer cell lines (HepG2 hepatocellular carcinoma, A549 lung cancer and U2OS osteosarcoma) along with the previously characterized glucose‐responsive gene STC2." (PMID 36047643, 2022). "After univariate cox regression analysis, lasso analysis and multivariate cox analysis, a five-gene signature (including HDAC1, BIRC5, SPP1, STC2, NR6A1) was constructed to predict the prognosis of hepatocellular carcinoma." (PMID 34616672, 2021).
gastric cancer (22 papers, 2013 to 2025). A primary or metastatic malignant neoplasm involving the stomach. "• Serum STC2 possesses diagnostic value in several cancers, especially gastric cancer." (PMID 34612765, 2021). "Overexpression of miR-1-3p inhibits the proliferation and invasion of gastric cancer cells by targeting stanniocalcin 2 (STC2) or centromere protein F (CENPF), in which CENPF is also associated with migration." (PMID 37907984, 2023). "Consistently, STC2 levels are higher in gastric cancer tissues than those in normal mucosa; elevated STC2 expression is correlated with tumour invasion, lymphatic metastasis and poor prognosis." (PMID 35501821, 2022). "In fact, miR-1-3p expression was shown to be severely downregulated in gastric cancer, and its mechanism of action was shown to include negative regulation of STC2 to suppress cell proliferation and invasion to form gastric cancer." (PMID 34407854, 2021). "In gastric cancer, miR-1-3p negatively regulated stanniocalcin 2 expression, thereby inhibiting cell proliferation and invasion." (PMID 33224315, 2020). "In gastric cancer patients, STC2 expression in circulating tumor cells as well as serum STC2 levels were positively correlated with pathological diagnosis and prognosis." (PMID 32296395, 2020). "The expression level of STC2 is dramatically increased in several cancers, including colon cancer, gastric cancer, prostate cancer and renal cancer." (PMID 27662663, 2016). "In gastric cancer, patients in the high STC2 expression group had a significantly poorer overall survival than those in the low STC2 expression group." (PMID 24606961, 2014). "The higher expression of STC2 was detected in 20 of 107 (18.7%) healthy volunteers, and in 101 of 112 (90.2%) patients with gastric cancer (χ2 = 113.1, P = 0.0001)." (PMID 23548070, 2013). "KAP1, TIMP1 and STC2 appear to have a role in the progression to metastatic disease in gastric cancer." (PMID 23548070, 2013). "High TIMP1 and STC2 expression levels were suspected to be poor prognostic factors of disease recurrence in patients with gastric cancer." (PMID 23548070, 2013). "In our study, the expression of STC2 in patients with gastric cancer was significantly higher than in healthy volunteers." (PMID 23548070, 2013). "In our study, the expression levels of STC2 in patients with gastric cancer were significantly higher than those in healthy volunteers." (PMID 23548070, 2013). "Expression levels of KAP1, TIMP1 and STC2 are potentially useful as clinical biomarkers for the screening, diagnosis, prognostic and surveillance of gastric cancer." (PMID 23548070, 2013). "We examined preoperative kinesin II-associated protein (KAP1), TIMP metallopeptidase inhibitor 1 (TIMP1) and stanniocalcin 2 (STC2) expression levels in patients with gastric cancers to assess their clinical application for diagnosing and monitoring diseases." (PMID 23548070, 2013). "cDNA microarray revealed elevated STC2 levels in gastric cancer comparing to normal tissues." (PMID 35501821, 2022). "Furthermore, blood STC2 levels have been shown to be a useful biomarker to screen and evaluate the prognosis of patients with gastric cancer." (PMID 35501821, 2022). "STC2 is a marker of poor prognosis in patients with gastric cancer or renal cell carcinoma." (PMID 33741523, 2021). "Several studies have revealed the clinical significance of STC2 in gastric cancer." (PMID 34612765, 2021). "STC2 served as an independent prognostic factor for gastric cancer patients." (PMID 34612765, 2021). "Conversely, the upregulation of STC2 weakened the inhibitory effect of miR-1-3p in gastric cancer." (PMID 34612765, 2021). "STC2 (Stanniocalcin 2) is a secreted glycoprotein with important functions in gastric cancer, which could be a powerful marker of poor prognosis." (PMID 32983633, 2020).
gastric cancer (continued). "In addition, we noted that some genes (such as CYP1A1, STC2, ASNS, etc.)listed in association with the tumour cell survival, cell proliferation, and cell death also affect the survival of gastric cancer patients under adjuvant chemotherapy." (PMID 30380689, 2018). "For example, a higher expression level of STC2 was detected in gastric cancer." (PMID 27662663, 2016). "KAP1, TIMP1 and STC2 expression levels may be potential biomarkers for the screening, diagnosis, prognosis and surveillance of gastric cancer." (PMID 23548070, 2013). "In particular, high TIMP1 and STC2 expression levels could be poor prognostic factors of disease recurrence in patients with gastric cancer." (PMID 23548070, 2013). "Furthermore, knocking down STC2 in gastric cancer cell line reduced the cell proliferation." (PMID 34612765, 2021). "In addition to tissue expression, STC2 was explored in sera from gastric cancer patients." (PMID 34612765, 2021). "In this study, we detected the expression of KAP1, TIMP1, STC2, TLN2, SRPX2, integrin beta 1 (ITGB1) and SPARC mRNAs in peripheral blood samples from pre-operative gastric cancer patients, patients with recurrence, and healthy volunteers." (PMID 23548070, 2013). "In this study, we detected the expression levels of KAP1, TIMP1, STC2, TLN2, SRPX2 and SPARC mRNAs in peripheral blood samples from pre-operative gastric cancer patients, those with recurrence, and in healthy volunteers." (PMID 23548070, 2013). "Moreover, STC2 overexpression in HNSCC was strongly correlated with reduced overall survival, consistent with reports that STC2 is a poor prognostic marker for patients with renal cell carcinoma and gastric cancer." (PMID 27863406, 2017). "The study showed that KAP1, TIMP1 and STC2 expression levels could differentiate preoperative gastric cancer patients from healthy volunteers, and that TIMP1 and STC2 could differentiate preoperative gastric cancer patients with recurrence from healthy volunteers." (PMID 23548070, 2013).
ovarian carcinoma (18 papers, 2014 to 2024). A malignant neoplasm originating from the surface ovarian epithelium. "STC2 was implicated in breast, cervical, and ovarian cancers, suggesting that it has hormone-specific or -dependent action in these malignancies." (PMID 32258098, 2019). "In ovarian cancer, overexpressed STC2 promotes epithelial-mesenchymal transition, as manifested by the increase in N-cadherin/vimentin loose fibroblastic colonies and the mesenchymal marker expression, and the decrease in epithelial marker expression." (PMID 35719372, 2022). "Consistently, a positive correlation between HMGA2 and STC2 IHC staining score is also revealed in human epithelial ovarian cancer samples." (PMID 35501821, 2022). "In our study, we demonstrated that knockdown of CREBBP dramatically decreased PERK/ATF4/STC2 expression, and promoted apoptosis in ovarian cancer cells treated with CDDP." (PMID 34149923, 2021). "Recent research suggested that STC2 was significantly increased in gastric cancer, ovarian cancer and liver cancer and other malignant tumors." (PMID 37287492, 2021). "Law and Wrong found that STC2 overexpression in ovarian cancer cell line SKOV3 increased proliferation rate and EMT under hypoxia conditions." (PMID 37287492, 2021). "Under hypoxic conditions, HIF-1α regulates increased STC2 expression to facilitate increased ovarian cancer tumor cell proliferation." (PMID 34867818, 2021). "Both STC1 and STC2 promote epithelial to mesenchymal transition in hypoxic ovarian cancer cells and contribute to their invasion and metastasis as well." (PMID 34867818, 2021). "It was also reported that overexpression of STC2 promotes ovarian cancer growth as well as promotes tumorigenicity and growth in colon cancer." (PMID 32296395, 2020). "This study confirmed STC2 as a HIF1α target gene that promotes cell proliferation in hypoxia in human breast and ovarian cancer cells." (PMID 32296395, 2020). "STC2 interference inhibits the proliferation of ovarian cancer cells, while its overexpression promotes proliferation." (PMID 32906580, 2020). "Our data are consistent with that previous conclusion which reported STC2 activates ERK levels to enhance ovarian cancer EMT and invasiveness." (PMID 27662663, 2016). "The expression of STC2 has been identified to be involved in a variety of cancers including renal, breast, and ovarian cancers." (PMID 25830567, 2015). "The expression of STC2 in vascular cells is correlated with decreased DFS in ovarian cancer." (PMID 35501821, 2022). "Taken together, STC2 plays an important role in ovarian cancer and is regulated by distinct signaling pathways, which may be dependent on cancer subtypes." (PMID 34612765, 2021). "Further studies are warranted to elucidate the function of STC2 in ovarian cancer." (PMID 34612765, 2021). "And STC2 also involves in ovarian cancer cell invasiveness activity." (PMID 27662663, 2016). "Therefore, the expression of STC2 was epigenetically inactivated in several ovarian cancer cells, which suggests that appropriate selection of cell lines is critical in STC2 research in ovarian cancer." (PMID 34612765, 2021). "Moreover, STC2 functions to protect cells from apoptosis in hypoxic ovarian cancer cell lines." (PMID 24606961, 2014). "In this prospective, longitudinal study of 107 women with ovarian cancer and ascites accumulation, we determined corresponding serum and ascites levels of IGF-1, IGF-2, PAPP-A, PAPP-A2, STC1, and STC2 and assessed their relationship with mortality." (PMID 38396692, 2024). "Stanniocalcin 2 (STC2) is a homologue of a glycoprotein hormone and closely correlated with rectal cancer, lung cancer, and ovarian cancer." (PMID 35780460, 2023). "Transwell assay revealed overexpression of STC2 enhances the invasion of ovarian cancer cells through matrigel or HUVEC -coated wells; in accordance, overexpression of STC2 upregulates MMP-2 expression and enhances the invasive ability of neuroblastoma cells." (PMID 35501821, 2022).
ovarian carcinoma (continued). "Healthy ovaries express both STC1 and STC2, and levels are increased in ovarian cancer compared to non-cancerous tissue." (PMID 38396692, 2024).
lung carcinoma (16 papers, 2016 to 2023). "Meanwhile, Kaplan-Meier OS curves suggested that high STC2 expression positively correlated with a poor prognosis in lung cancer." (PMID 36685853, 2022). "High expression of SERPINE1 and STC2 in lung cancer tissues of NSCLC patients (n = 5) and low expression of LPCAT1 in the NSCLC group were confirmed at the mRNA level compared to those in the normal lung tissues (n = 5)." (PMID 35634481, 2022). "Kaplan-Meier OS curves suggested that high STC2 expression positively correlated with a poor prognosis in lung cancer." (PMID 36685853, 2022). "Stc2/Jun/Axl signal activation can mediate the acquired resistance of lung cancer patients to EGFR tyrosine kinase inhibitors." (PMID 35634481, 2022). "The acquired resistance of lung cancer patients to EGFR tyrosine kinase inhibitors is mediated by reactivation of the stc2/Jun/Axl signal." (PMID 35634481, 2022). "The overexpression of STC2 was observed in lung cancer cells, and knockdown of STC2 suppressed the growth, colony formation, invasion, and metastasis of cancer cells." (PMID 34612765, 2021). "The overexpression of STC2 was observed in lung cancer cells, and knock-down of STC2 suppressed growth, colony formation, invasion, and metastasis of cancer cells." (PMID 32258098, 2019). "A study had reported higher mRNA and protein expressions of STC2 in lung cancer tissues compared to the adjacent normal tissue." (PMID 27028764, 2016). "Moreover, overexpression of STC2 has been observed in lung cancer cells, and STC2 knockdown has been shown to inhibit the growth, colony formation, invasion, and metastatic capacity of cancer cells." (PMID 36698399, 2022). "The overexpression of STC2 in lung cancer tissues was also observed." (PMID 32258098, 2019). "Knockdown of STC2 slowed down lung cancer cell growth progression, colony formation and metastasis." (PMID 27028764, 2016). "Importantly, elevated STC2 levels are correlated with poor prognosis in patients with lung cancer." (PMID 35501821, 2022). "Additionally, STC2 exerted a protective effect on the redox system of lung cancer." (PMID 32258098, 2019). "We subsequently identified a key gene, STC2, whose expression was up-regulated by PM2.5 and correlated with a poor prognosis in lung cancer." (PMID 36685853, 2022).
head and neck squamous cell carcinoma (15 papers, 2017 to 2024). A squamous cell carcinoma that arises from any of the following anatomic sites: lip and oral cavity, nasal cavity, paranasal sinuses, pharynx, larynx, and salivary glands. "Another work showed that STC2 was associated with head and neck squamous cell carcinoma cell proliferation through GSEA analysis." (PMID 34249085, 2021). "It plays the same role in cancer, just like the HOTAIR / miR-206 / STC2 axis in head and neck squamous cell carcinoma." (PMID 36115953, 2022). "In head and neck squamous cell carcinoma, STC2 promotes metastasis through modulating the PI3K/AKT/Snail signaling." (PMID 35646113, 2022). "In head and neck squamous cell carcinoma, STC2 promotes tumor and its correlationship with clinical parameters needs to be further analyzed." (PMID 34612765, 2021). "In head and neck squamous cell carcinoma, STC2 is regulated by microRNA-206 and influences cell proliferation and invasion." (PMID 33952718, 2021). "It was reported that STC2 could promote head and neck squamous cell carcinoma metastasis by modulating the PI3K/AKT/snail signaling pathway." (PMID 34079579, 2021). "However, the exact function of STC2 in human head and neck squamous cell carcinoma (HNSCC) is unclear." (PMID 27863406, 2017). "In head and neck squamous cell carcinoma, the overexpression of STC2 suppressed cell apoptosis, promoted cell proliferation, migration, invasion, and delayed the cell cycle at the G1/S phase; all these phenomena could be reversed by knocking down STC2." (PMID 34612765, 2021). "Long noncoding RNA HOTAIR was reported to accelerate the proliferation, migration, and invasion of head and neck squamous cell carcinoma (HNSCC) cells by sponging microRNA-206 and targeting STC2." (PMID 32528555, 2020). "The analysis of tumor samples from patients with lymph node metastasis revealed that the expression of STC2 was correlated with the levels of AKT and Snail, thereby suggesting that STC2 may promote head and neck squamous cell carcinoma via PI3K/AKT/Snail pathway." (PMID 34612765, 2021).